SLC35E3 (solute carrier family 35 member E3)
Description:
Putative transporter.
Synonyms: BLOV1
Tractability: Antibody: UniProt predicts a signal peptide or a membrane-spanning region. PROTAC: ubiquitination databases record sites on it.
Gene: Protein-coding gene on chromosome 12 (68,746,125 to 68,793,964, forward strand). Ensembl gene ENSG00000175782.
Subcellular location: Membrane
Gene Ontology:
Molecular function: protein binding
Cellular component: membrane
Genetic constraint (gnomAD): Loss-of-function variants: 20 observed, 22.95 expected, observed/expected ratio (o/e) 0.87, 90% interval 0.61 to 1.27. The upper end of that interval is the gene's LOEUF score, 1.27, which puts it in group 5 of 6, group 1 being the genes least tolerant of losing a copy. Missense variants: 301 observed, 316.98 expected, observed/expected ratio (o/e) 0.95, 90% interval 0.86 to 1.04. Synonymous variants: 122 observed, 132.06 expected, observed/expected ratio (o/e) 0.92, 90% interval 0.8 to 1.07.
Homologues: Orthologues: chimpanzee SLC35E3 (99% identical), macaque SLC35E3 (98% identical), guinea pig SLC35E3 (95% identical), pig SLC35E3 (94% identical), rat Slc35e3 (93% identical), mouse Slc35e3 (92% identical), zebrafish slc35e3 (82% identical). Paralogues in human: SLC35E2B (22% identical), SLC35H1 (21% identical), SLC35E4 (20% identical), SLC35C1 (19% identical), SLC35E1 (19% identical), SLC35D2 (19% identical), SLC35D1 (18% identical), SLC35D3 (17% identical), SLC35D4 (16% identical).
Diseases named in the same sentence as SLC35E3 in open-access papers:
SLC35E3 is named in the same sentence as 4 diseases in open-access papers, as found by Europe PMC text mining. Sharing a sentence is not in itself a finding about the gene and the disease. The quoted sentences say what the papers report.
bladder cancer (1 paper, 2017). "SLC35E3, also called Bladder Cancer-Overexpressed gene 1 (BLOV1), acts in transmembrane transport and belongs to the drug/metabolite transporter protein superfamily (Luscombe, MJ, A novel gene which is overexpressed in advanced bladder cancer May 1999, EMBL/GenBank/DDBJ databases)." (PMID 28589857, 2017).
cardiac hypertrophy (1 paper, 2020). "Interestingly, Slc35e3 was found to be up-regulated during cardiac hypertrophy, while Slc25a36 has been previously identified to be involved in the metabolism of nucleic acids in cardiac cells." (PMID 33102519, 2020).
liposarcoma (1 paper, 2025). A usually painless malignant tumor that arises from adipose tissue. "Key genes in this region, including MDM2, cyclase-associated protein (CPM), and solute carrier family 35 member E3 (SLC35E3), are significantly amplified and play a critical role in the progression of dedifferentiated liposarcoma." (PMID 39974236, 2025).
SLC35E3 also shares sentences with these, for which no sentence is quoted: cancer (1 paper).